OCRL (OCRL inositol polyphosphate-5-phosphatase)
Diseases named in the same sentence as OCRL in open-access papers (continued):
Sharing a sentence is not in itself a finding about the gene and the disease.
cataract (7 papers, 2010 to 2025). Partial or complete opacity of the crystalline lens of one or both eyes that decreases visual acuity and eventually results in blindness. "However, very little is known how defects in OCRL results in cellular dysfunction that underlies cataracts formation and the defective flow of aqueous humor that leads to congenital glaucoma." (PMID 23805271, 2013).
Hypercalciuria (6 papers, 2015 to 2025). "When OCRL is defective, there is a consequent loss of physiological TRPV6 inhibition, and this could pave the way to hypercalciuria through an increased intestinal absorption of Ca2+." (PMID 32860533, 2021). "The authors recommended screening for CLCN5 and/or OCRL mutations in all males presenting with LMWP irrespective of any additional clinical features (nephrolithiasis or nephrocalcinosis, hypercalciuria, rickets, or CKD)." (PMID 32860533, 2021).
Fanconi syndrome (4 papers, 2020 to 2024). "The renal phenotype associated with OCRL mutations typically comprises a selective proximal tubulopathy, which can manifest as Fanconi syndrome in the most extreme cases." (PMID 31811534, 2020).
cognitive deficits (3 papers, 2011 to 2025). "Overall, our study provides insights into the cellular and developmental mechanism by which OCRL loss in LS patients may lead to cognitive deficits evident at birth and during early childhood." (PMID 41219536, 2025).
cystinosis (2 papers, 2020 to 2021). Cystinosis is a metabolic disease characterized by an accumulation of cystine inside the lysosomes, causing damage in different organs and tissues, particularly in the kidneys and eyes. "Besides CLCN5 (DD1) and OCRL (Lowe syndrome and Dent disease type 2) genes, they include LRP2 (DB/FOAR), CUBN, AMN (Imerslund–Gräsbeck syndrome), and CTNS (nephropathic cystinosis)." (PMID 31947599, 2020).
focal segmental glomerulosclerosis (2 papers, 2021 to 2025). A renal disorder characterized by sclerotic lesions in the glomeruli. "Emerging evidence also suggests that ClC-5 and OCRL may be expressed in human podocytes, potentially explaining the development of focal segmental glomerulosclerosis (FSGS) lesions observed in kidney biopsies of patients with DD1 and DD2." (PMID 39794284, 2025).
renal dysfunction (2 papers, 2020 to 2021). "This study reports two novel OCRL variants associated with severe ocular and neurologic deficiency, despite only mild renal dysfunction." (PMID 34488756, 2021).
Alzheimer disease (1 paper, 2025). A progressive, neurodegenerative disease characterized by loss of function and death of nerve cells in several areas of the brain leading to loss of cognitive function such as memory and language. "To further examine the relationship between OCRL and Alzheimer’s disease pathology, we performed double immunofluorescence staining for phosphorylated tau (pTau, using the AT8 antibody) and OCRL." (PMID 40565289, 2025).
amyloid (1 paper, 2025). "In vivo studies using transgenic mouse models with OCRL overexpression or knockdown in the context of amyloid or tau pathology will be essential to address this question." (PMID 40565289, 2025).
asthma (1 paper, 2022). "Through machine learning and bioinformatics techniques, four hub genes, including HIF1A, NNMT, OCRL, and PER1, were identified as potential markers associated with asthma metabolism, especially HIF-1A." (PMID 36676950, 2022). "In this study, four hub genes including HIF1A, OCRL, NNMT, and PER1 were identified as potential markers associated with asthma metabolism by bioinformatics analysis." (PMID 36676950, 2022). "In the present study, we merged the differentially expressed genes (DEGs) of asthma in the GEO database with the metabolic genes obtained by Genecard for bioinformatics analysis and successfully screened out the metabolism-related hub genes (HIF1A, OCRL, NNMT, and PER1)." (PMID 36676950, 2022).
breast carcinoma (1 paper, 2022). "From the results, we found that mRNA expressions of SLC19A1, CYC1, RRM2B, and OCRL were clearly elevated in breast cancer, while RPS14 expression was considerably decreased." (PMID 35574387, 2022). "And for the survival analyses of OS, high expressions of SLC19A1, CYC1, RRM2B, and OCRL and downregulation of RPS14 were significantly related to more unfavorable OS in breast cancer, which further confirmed the validity of selected genes." (PMID 35574387, 2022). "By performing the LASSO Cox regression analysis with 9 candidate genes in breast cancer patients of TCGA-BRCA training dataset, 5 pivotal genes were unearthed to establish the prognostic signature, Lactate Metabolism Index, namely LMI, including RPS14, SLC19A1, CYC1, RRM2B, OCRL." (PMID 35574387, 2022).
chronic progressive external ophthalmoplegia (1 paper, 2024). "Another patient suspected to have chronic progressive external ophthalmoplegia (CPEO) due to mitochondrial disease showed a missense mutation in OCRL." (PMID 39553960, 2024).
epilepsy (1 paper, 2024). A brain disorder characterized by episodes of abnormally increased neuronal discharge resulting in transient episodes of sensory or motor neurological dysfunction, or psychic dysfunction. "Regarding the etiology of epilepsy, five (11.1%) were genetic, including one with SCN2A mutation, one with KCNA2 mutation, one with MBD5 mutation, one with WFS1 mutation, and one with OCRL mutation." (PMID 38419715, 2024).
liver diseases (1 paper, 2021). "Likewise, a lack of an association of OCRL and BA or liver diseases remains a gap for future investigation." (PMID 34750413, 2021).
osteoarthritis (1 paper, 2017). A noninflammatory degenerative joint disease occurring chiefly in older persons, characterized by degeneration of the articular cartilage, hypertrophy of bone at the margins and changes in the synovial membrane. "More recently, it was shown that downregulation of the Rac1 GAP, inositol polyphosphate 5-phosphatase OCRL-1 (OCRL1), in cartilages is responsible for the aberrant activation of Rac1 in osteoarthritis." (PMID 27442895, 2017).
Parkinson disease (1 paper, 2015). A progressive degenerative disorder of the central nervous system characterized by loss of dopamine producing neurons in the substantia nigra and the presence of Lewy bodies in the substantia nigra and locus coeruleus. "We have employed this method to GFP tag OCRL (a phosphoinositide-5-phosphatase in the endocytic pathway) and Vps35 (a Parkinson's disease-implicated component of the endosomal retromer complex) in diverse Drosophila tissues including neurons, glia, muscles and hemocytes." (PMID 26700726, 2015).
cancer (4 papers, 2018 to 2025). A tumor composed of atypical neoplastic, often pleomorphic cells that invade other tissues. "As for OCRL, the role in cancer remained to be further elucidated by experiments." (PMID 35574387, 2022). "Moreover, other genes from diverse functional groups appeared in our analysis, such as signal transducers promoting cancer growth (CD53, RAB33A, GNA11, CANX, OCRL, GIPC1, and SOS1), microtubule formation (KIF21B) and cell migration (ASAP2)." (PMID 29535628, 2018).
neurologic disorders (1 paper, 2024). "LS patients with OCRL mutations develop a wide range of neurologic disorders." (PMID 39553960, 2024).
OCRL also shares sentences with these, for which no sentence is quoted: Dent disease type 2 (9 papers); congenital cataracts (5); Dent disease type 1 (4); Intellectual disability (4); Joubert syndrome (4); kidney disease (4); nephrocalcinosis (4); nephrolithiasis (3); renal Fanconi syndrome (3); genetic disorder (2); hypophosphatemia (2); infection (2); Nephropathy (2); nephrotic syndrome (2); neurodevelopmental disorder (2); renal failure (2); Alport syndrome (1); Ataxia (1); autism (1); Barth syndrome (1); brain disease (1); Charcot-Marie-Tooth disease (1); colon cancer (1); congenital glaucoma (1); congenital myopathies (1); corneal dystrophy (1); cyst (1); deafness (1); distal renal tubular acidosis (1); Dowling-Degos disease (1).
A further 31 diseases each share a sentence with OCRL in 1 paper.